PPARA (peroxisome proliferator activated receptor alpha)
Diseases named in the same sentence as PPARA in open-access papers (continued):
Sharing a sentence is not in itself a finding about the gene and the disease.
cancer (continued). "Given that PPARα regulates the expression of CD36 in fatty acid metabolism, it may be possible in the future to utilize PPARα to inhibit CD36 expression or block its function, thereby providing a potential therapeutic approach for inhibiting cancer cell metastasis." (PMID 38004166, 2023). "Unlike its role in angiogenesis, PPARα′s effect on immune cells in TME is often pessimistic, ultimately leading to immunosuppression or even cancer immune escape." (PMID 37251321, 2023). "Although activation of the PPARα by its agonists has been shown to inhibit cancer growth including HCC cell lines, there have been no studies to mechanistically define the role of PPARα in hepatocarcinogenesis." (PMID 25327562, 2014). "Moreover, in normal cells, PPARα antagonist did not inhibit the glycolysis; conversely, in RCC, cell line glycolysis was attenuated, which was likely due to a difference of c-Myc protein levels between cancer cells and normal cells." (PMID 29966227, 2018). "In addition, PPARα can target the regulatory region of the HILPDA gene to enhance TAG storage in hepatocytes, although this PPAR-HIG2 axis has not been demonstrated in cancer cells (route 17)." (PMID 27589734, 2016).
tumor (524 papers, 2005 to 2026). "PFOS increased carcinogenic risk, tumor progression and spheroid formations in the prostate gland as well as increased the expression of PPARα and RXRα." (PMID 41228300, 2025). "The other study reported that low PPARα expression is associated with clinical features such as tumor size, TNM stage, and distant metastasis in HCC." (PMID 40936093, 2025). "PPARα, the main isoform expressed in the liver, is found in differentiated tumor-derived hepatocytes, associated with high PGC1α expression, branched mitochondrial network and OXPHOS." (PMID 41249163, 2025). "TPST-1120 is a first-in-class oral inhibitor of PPARα, whose roles in metabolic and immune regulation are implicated in tumor proliferation/survival and inhibition of anticancer immunity." (PMID 38551394, 2024). "First, the synthetic PPARα agonists fenofibrate and Wy-14643 have been shown to inhibit vascular endothelial cell proliferation and tumor xenograft growth, whereas mice with PPARα deficiency showed a notable (p < 0.05) increase in neovascularization." (PMID 37251321, 2023). "Promising experimental findings on the anti-tumor activity of pioglitazone face the difficulty of missing monoactivity in metastatic tumor disease, despite of the very low mutation rate of PPARα/γ in human tumor cells." (PMID 38273846, 2023). "Previous studies have shown that PPARβ/δ activation is associated with tumor progression, whereas PPARα and PPARγ activation is associated with tumor suppression." (PMID 37251321, 2023). "PPARα deficiency has further been demonstrated to inhibit tumor growth by impairing regulatory T-cell (Treg) functions and by supporting a pro-inflammatory Th1 T-cell phenotype." (PMID 35954274, 2022). "PPARα deficiency in the host suppressed tumor growth via the induction of a plain inflammation capable of suppressing tumor angiogenesis, mainly through increased production of thrombospondin (TSP)-1." (PMID 35954274, 2022). "Early investigations revealed that, in the majority of cases, the activation of PPARβ/δ is linked to tumor progression, whereas PPARα and PPARγ are associated with anti-tumorigenesis." (PMID 33946986, 2021). "PPARα deficiency induced a strong inflammatory response with an excess of TSP-1 production leading to suppression of tumor angiogenesis." (PMID 32785018, 2020). "Previous studies have reported that the levels of Cyp2c44 expression and EET biosynthesis, which are positively associated with tumour growth and angiogenesis, were controlled by PPARα activation in the endothelium." (PMID 31791289, 2019). "The demonstration of a direct interaction at the nuclear level between HMGCS2 and PPARα is interesting; besides, other analyses confirmed that the heterodimeric complex binds the Src promoter region and induced genes linked to tumor invasion." (PMID 29966227, 2018). "Increasing evidences show that PPARα or PPARγ inhibits tumor progression, which acts as tumor suppressors, while some reports show that PPARα is associated with tumor progression." (PMID 28948004, 2017). "PPARα was associated with tumor grade (P < 0.0001 for both Rembrandt data and GSE4290 data), which is consistent with the CGGA data." (PMID 27835866, 2016). "Neutrophils have also been reported to produce angiostatin itself and are associated with anti-angiogenic tumor repression in peroxisome proliferator-activated receptor alpha (PPARα) deficient mice." (PMID 25072019, 2014). "Peroxisome proliferators activated receptor alpha (PPARα), a ligand-inducible nuclear transcription factor that has been implicated in the pathogenesis and treatment of tumor including lung cancer." (PMID 23867003, 2013). "PPARα, a ligand-inducible nuclear transcription factor that has been implicated in the pathogenesis and treatment of tumor including lung cancer both in vitro and in vivo." (PMID 23867003, 2013).
tumor (continued). "To further analyze the link between NOX1 and PPARα in vivo, we injected LLC1 or B16F0 tumor cells in either WT or PPARα-deficient mice and treated these animals with the NOX1 inhibitor GKT136901." (PMID 21326871, 2011). "Lossof PPARα leads to an increased infiltration tothe side of injury of granulocytes that suppress tumor-associated angiogenesisvia excess production of the endogenous angiogenesis inhibitor thrombospondin." (PMID 18725983, 2008). "Another possibility is that in PPARα deficient mice, stromal processes, such as inflammation, inhibit tumor growth, which results in microscopic-sized tumors that remain dormant." (PMID 17327920, 2007). "In fact, we found that deletion of PPARα in the tumor cell itself potentiated the tumor suppressing effect of PPARα-deficiency in the host tissue, in agreement with the earlier reports of the requirement for PPARα in PPARα agonist induced liver tumors." (PMID 17327920, 2007). "In this study we identified the cellular basis for the tumor suppressing phenotype of PPARα deficient mice." (PMID 17327920, 2007). "Purified peripheral blood leukocytes from tumor- bearing PPARα deficient mice expressed high levels of TSP-1 while WT leukocytes express very little if any TSP-1." (PMID 17327920, 2007). "To corroborate an active role of these PPARα-deficient granulocytes in tumor suppression, we depleted them in the host animals." (PMID 17327920, 2007). "Bone marrow cells from WT mice were capable of restoring the “wild-type” tumor growth pattern of B16-BL6 tumors in PPARα deficient hosts." (PMID 17327920, 2007). "Conversely, PPARα-deficient bone marrow cells, when transplanted into WT hosts, conferred the tumor-suppressing phenotype of PPARα KO mice, p<0.0001." (PMID 17327920, 2007). "Furthermore, loss of PPARα expression in host animals inhibited tumor growth in lung cancer cells according to a study using a mouse xenograft model." (PMID 38189049, 2023). "Thus, the carcinogenicity profile for HFPO-DA is consistent with other PPARα activators, inducing changes in the 3 tissues in the rat associated with the tumor triad." (PMID 36629480, 2023). "Using a PPARα-humanized mouse (hPPARα) model, where the human PPARα gene was introduced onto a PPARα deficient background, they determined that tumor angiogenesis and growth were inhibited in animals which received Wyeth (pirinixic acid, a potent PPARα agonist)." (PMID 32785018, 2020). "It has been reported that after the retinoic acid/PPARα pathway is disrupted, it will affect oxidative damage and change the expression of tumor suppressors, which may lead to colorectal tumors caused by low folic acid intake." (PMID 33029112, 2020). "Thus, the toxicity profile for GenX is consistent with other PPARα activators, inducing changes in the three tissues associated with the tumor triad." (PMID 31215065, 2019). "Indeed, PPARα knockout mice are more susceptible to carcinogen-induced HCC, suggesting that PPARα inhibits tumor formation in this model." (PMID 27351284, 2016). "However, in the DEN tumor induction model, loss of PPARα in mice resulted in a significant increase in HCC development compared to WT animals." (PMID 25327562, 2014). "Here we show that PPARα deficiency in the host leads to overt inflammation that suppresses angiogenesis via excess production of the endogenous angiogenesis inhibitor thrombospondin-1 and prevents tumor growth." (PMID 17327920, 2007). "Neutralization of thrombospondin-1 restores tumor growth in PPARα-deficient mice." (PMID 17327920, 2007). "We next asked why are tumor growth and angiogenesis inhibited by PPARα-deficient leukocytes?" (PMID 17327920, 2007). "One study showed that extraperoxisomal effects of PPARα agonists that may be related to tumor induction are effects on mitochondria, which have a role in several aspects of tumor biology and whose DNA may have increased susceptibility." (PMID 16966106, 2006).
tumor (continued). "However, Kaipainen and colleagues evidenced a tumor-suppressive phenotype in PPARα-deficient mice." (PMID 35954274, 2022). "While NF-κB exerts its tumor-promoting effect by induction of cytokines, we investigated whether PPARα deficiency suppresses tumor growth by increasing the expression of the matrix protein thrombospondin-1 (TSP-1) which inhibits angiogenesis and stimulates granulocyte migration." (PMID 17327920, 2007). "The only neoplasms in the chronic mouse bioassay were in the liver and were considered PPARα related." (PMID 41968070, 2026). "We found that tumor‐derived CCL2 acitively upregulates PPARα, a key transcription factor in lipid metabolism, thereby promoting adipose lipolysis and the release of FAs." (PMID 41160815, 2026). "Future work should extend these findings in vivo by employing xenograft or genetically engineered mouse models of EBVaGC to evaluate the impact of miR-BART20-3p inhibition or PPARα activation on tumor growth and metastasis." (PMID 40732023, 2025). "THP-1 cells expressing increased ACE (termed THP-1-ACE) constitute a human macrophage model with increased PPARα that shows enhanced cytotoxicity against tumor cells and better phagocytosis and killing of MRSA." (PMID 39910334, 2025). "N-acylethanolamine acid amidase inhibitor AM9053 inhibits tumor cell growth, proliferation, and migration via PPARα and TRPV1 in CRC cells." (PMID 39875357, 2025). "In contrast, the in vivo administration of pemafibrate, a specific agonist of PPARα, to WT and A10-PPARα-Cre mice reduced B16-F10 tumor growth by 24.5% and 25.8%, respectively, but pemafibrate reduced tumors by 57.8% in ACE10/10 mice." (PMID 39910334, 2025). "Early studies have shown that PPARα agonists reduce transcriptional activation of COX-2 and VEGF, which are associated with tumor angiogenesis." (PMID 39875357, 2025). "Reduced PPARα protein expression decreased the tumor-killing effect of THP-1 and THP-1-ACE macrophages." (PMID 39910334, 2025). "By affecting PPARα, PPARβ, and PPARγ activity, engineered exosomes can reprogram macrophages and impair metabolic support to the tumor, ultimately reducing tumor viability and growth." (PMID 40754671, 2025). "We confirmed that both PPARα mRNA and protein are reduced in EBVaGC cell lines and primary tumor specimens, and that this reduction inversely correlates with miR-BART20-3p levels." (PMID 40732023, 2025). "In CRC, with tumor progression, increased expression of PPARα and PPARβ/δ or decreased expression of PPARγ." (PMID 39875357, 2025). "Our results highlight, for the first time, a balanced expression of PPARα and PPARγ along the tumor-derived hepatocyte differentiation/retrodifferentiation process." (PMID 41249163, 2025). "Conversely, within acidic tumor microenvironments, upregulated PPARα fuels cancer cell proliferation and invasion by enhancing FAO and lipid droplet (LD) accumulation, thereby supporting the energy demands of acid-adapted CRC cells." (PMID 40718481, 2025). "Previous studies have shown that PPARα gene knockout reduces cytotoxic T cell activity, binds to the PD-L1 promoter, and blocks its transcription, inhibiting tumor immune evasion." (PMID 41285764, 2025). "The tumor-killing effect of A10-PPARα TPMs was greater than that of equivalent cells from WT mice, whereas PPARα reduction in A10-PPARα-Cre TPMs was similar to that in WT cells." (PMID 39910334, 2025). "RNA silencing of PPARα in THP-1-ACE cells reduced both tumor cell death and bacterial phagocytosis and clearance." (PMID 39910334, 2025). "The tumor-killing effect, bacterial phagocytosis, and bactericidal effect were significantly greater in PPARα-overexpressing THP-1 macrophages than in control cells." (PMID 39910334, 2025). "In other words, PPARα positively responded to the tumor-derived exosomes-mediated increase in lipid levels, which induced lipid droplets generation and FAO enhancement, resulting in DC immune dysfunction." (PMID 39875357, 2025).
tumor (continued). "Although the anti-angiogenic effect of PPARα is well documented, some studies have demonstrated that it can also promote tumor angiogenesis." (PMID 39875357, 2025). "Targeting PPARγ, a key regulator of metabolic reprogramming and stemness in hepatic CSCs, or modulating the PPARγ/PPARα balance that finely tunes the differentiation/retrodifferentiation process in HCC deserves further investigation for anti-tumor therapy." (PMID 41249163, 2025). "For instance, PPARα and PPARγ mainly act as a tumor suppressor and a promoter, respectively, during tumor progression, whereas PPARβ/δ plays a controversial role in tumorigenesis." (PMID 39519311, 2024). "Another study reported that inhibition of PPARα activity restored the anti-tumor effect of dendritic cells." (PMID 38746124, 2024). "Reduced PPAR activity was also associated with reduced PPARα/RXRα activity, while LPS/IL1-mediated inhibition of RXR activity was significantly activated in the tumor datasets." (PMID 39195246, 2024). "Promoting FAO with a PPARα agonist further improved the ability of CD8+ TILs to slow tumor progression." (PMID 39402302, 2024). "High expression of PPARα can decrease tumor cell growth by inhibiting cell division and triggering cell death through IκBα and NF-κB pathways." (PMID 38920644, 2024). "In the tumor tissue of KIRC patients, we discovered a notable association between PPARA and TKTL1 expression, which is a part of the peroxisome proliferator-activated receptor." (PMID 38675412, 2024). "Smaller but significant reductions in PPARα mRNA expression and activity were also seen, suggesting a potential tumor suppressor role for PPARα as well." (PMID 39195246, 2024). "In conclusion, these data provide strong evidence that PPARγ and possibly PPARα represent key tumor suppressors by acting as master inhibitors of the inflammatory changes found in AKs and SCCs." (PMID 39195246, 2024). "In response to conditions such as hypoglycemia and hypoxia, tumor-infiltrating CD8+ T cells increase PPARα signaling and fatty acid catabolism to maintain energy production and effector functions." (PMID 39402302, 2024). "These tumor-derived exosomes (TDEs) were found to induce PPARα in DCs, leading to fatty acid accumulation and oxidation, resulting in a shift towards mitochondrial oxidative phosphorylation." (PMID 39327610, 2024). "Interestingly, tumor-derived exosomes carrying excessive fatty acids to DCs contribute to decreased antigen presentation through the Peroxisome Proliferator Activated Receptor α (PPARα)-mediated metabolic reprogramming linked to enhanced lipid droplet biogenesis and fatty acid oxidation." (PMID 39188677, 2024). "Previous studies suggest that PPARA is a tumor suppressor in some cancers, including melanoma and glioblastoma." (PMID 36424525, 2023). "Therein, it was shown that HFPO-DA is not genotoxic, but induced cancers in Sprague Dawley rats in a pattern consistent with the PPARα tumor triad of liver adenomas/carcinomas, testicular Leydig cell tumors and pancreatic acinar cell tumors." (PMID 36629480, 2023). "PPARα agonist induced chemokine expression in the tumor (CXCL9/10) together with the respective receptor (CXCR3) on CD8+ T-cells, allowing their recruitment into the tumor tissue microenvironment." (PMID 37686465, 2023). "Since PPARα activation can induce apoptosis in a variety of tumor cells and venetoclax inhibits the anti-apoptotic protein Bcl-2, the apoptosis of KG-1α cells was assessed by flow cytometry using Annexin V/PI staining." (PMID 37644011, 2023). "Oxadiazone, an N-phenyl heterocycle compound, induces tumor development by activating PPARα, inducing CYPa10 and CYP4A." (PMID 36875280, 2023). "When activated, PPARα exhibits antiangiogenic and anti-inflammatory effects, thereby inhibiting tumor development." (PMID 38189049, 2023). "PPARα is a nutrient sensor and can be activated by dietary polyunsaturated FAs (PUFAs), providing a potential strategy for tumor prevention through diet." (PMID 37084728, 2023).